PLXND1 (plexin D1)
Diseases named in the same sentence as PLXND1 in open-access papers (continued):
Sharing a sentence is not in itself a finding about the gene and the disease.
tumor (continued). "Additionally, PLXND1 expression was related with tumor-infiltrating lymphocytes (TILs) and immunoinhibitors, and TGF-β1 displayed the greatest correlations with PLXND1 expression in HCC." (PMID 33489909, 2020). "In summary, based on our systematic analyses of NRPs and PLXNs in terms of their expression, association with patient survival, immune subtype, and tumor infiltration, we found that NRP1, NRP2, PLXNA1, PLXNA3, PLXNB3, PLXNC1, PLXND1 were mainly associated with poor prognosis." (PMID 32640719, 2020). "For example, as a repulsive cue for Plexin D1-expressing endothelial cells, overexpression of Sema3E inhibits tumor development via the disruption of tumor vascular patterning; similarly, recombinant Sema3E can inhibit PDGF-mediated proliferation and migration of human airway smooth muscle cells." (PMID 26036259, 2015). "In ovarian endometrial carcinomas, we have provided a previously unknown mechanism of Sema3E/Plexin-D1 signaling that facilitates tumor progression through Snail1-medidated EMT." (PMID 21559368, 2011). "Apart from tumor-associated endothelium and tumor cells, PLXND1 expression was also observed in subsets of fibroblast- and macrophage-like cells in both tumor samples and pre-malignant and non-tumor related tissues." (PMID 19703316, 2009). "So, for subsets of tumor types in which vessel activation has occurred, PLXND1 may be a valuable candidate protein for vascular targeting approaches." (PMID 19703316, 2009). "Plexin D1 expression in pre-malignant and non-tumor related tissues." (PMID 19703316, 2009). "The objective of this study was to examine whether Plexin D1 might be clinically useful as a pan-tumor vessel and pan-tumor cell target in solid tumors." (PMID 19703316, 2009). "PLXND1 contains in its intracellular domain consensus Rac/RhoA signalling motifs, suggestive of a role in cytoskeletal rearrangements and cell motility, processes which are fundamental for both tumor angiogenesis and metastasis." (PMID 19703316, 2009). "To explore whether PLXND1 may be clinically useful as a pan-tumor endothelium and a pan-tumor cell target we examined the expression profile of this protein in a large variety of human tissue samples." (PMID 19703316, 2009). "Besides vascular expression, high PLXND1 expression was also found on tumor cells in cerebral melanoma metastases." (PMID 19703316, 2009). "Apart from vascular PLXND1 expression in tumors, the protein is also abundantly expressed on tumor cells in a wide range of clinical solid tumors which reinforces this membrane protein as a tumor target, since it allows simultaneous targeting of different tumor compartments with one compound." (PMID 19703316, 2009). "In addition, NRP1, PLXNB2, and PLXND1 also showed increased expression in immune subtype C3, which is correlated with better prognosis, indicating these genes may also play tumor suppressor roles in certain conditions." (PMID 32640719, 2020). "Emerging data have shown that PLXND1 could function as a tumor suppressor or a classical oncogene." (PMID 33489909, 2020). "However, sema3C also functions as a potent inhibitor of angiogenesis and lymphangiogenesis, which is likely mediated by the activation of plexin-D1-dependent signal transduction in endothelial cells and lymphatic endothelial cells, resulting in the inhibition of tumor progression." (PMID 30696103, 2019). "Similarly, the oxidized low-density lipoprotein receptor 1 (OLR1) gene, which plays an important role in the humoral immunity of the skin, and the plexin D1 (PLXND1) gene, which is highly expressed in tumor vasculature, were both found to be common targets of miR-27b, miR-1914, and miR-612." (PMID 31766385, 2019). "Indeed, the anti-PLXND1 single domain antibody A12 homes to and accumulates in tumor vessels." (PMID 19703316, 2009).
tumor (continued). "Due to vessel heterogeneity in tumors it is unlikely that one single marker will behave as a targetable pan-tumor-endothelial antigen, but appropriate mixtures of different tumor vessel targeting agents, including anti-PLXND1 antibodies, may allow specific targeting of the majority of tumor vessels." (PMID 19703316, 2009). "PLXND1 may thus be functionally involved in tumor development in multiple ways." (PMID 19703316, 2009). "Knockdown or knockout of PLXND1 inhibit neural lineage pathways, suppressing NEPC cell proliferation, PDX tumor organoid viability, and xenograft tumor growth." (PMID 38585965, 2024). "While fibroblast cells, like tumor cells, expressed EGFR and FGFR1, they also exclusively expressed higher levels of the receptors LRP1, PDGFRs, and PLXND1 in both patients." (PMID 34459128, 2021). "We have found that in HCC, PLXND1 expression was correlated with TGF-β1, which is a well-known modulator involved in tumor formation, invasion, and metastasis." (PMID 33489909, 2020). "Multivariate analysis further identified that only the expression of PLXND1 and TGF-β1, stage, TH, tumor number, and satellite nodules behaved as independent predictors for both OS and RFS." (PMID 33489909, 2020). "The pro-angiogenic effect of Sema4A in the context of tumor is indirectly mediated by signaling through Plexin-D1-expressing macrophages, which induce VEGF-A expression and thereby enhance tumor vasculature." (PMID 32210960, 2020). "In conclusion, we first report that PLXND1 is overexpressed in HCC and shows a significant correlation with several clinicopathological features, including tumor stage and TH." (PMID 33489909, 2020). "The tumor cells adapting to brain tissue do provide several pro-angiogenic functions temporarily, e.g. in BN25 15, Plxnd1, Vangl2, Fzd2, Fzd5, and Vegfa promote patterning of blood vessels and vascular development." (PMID 25004123, 2014). "Some of these genes were upregulated in our analyses of skin KS (BTAF, VMP1, DCHS1, VCAM1, PLXND1)." (PMID 37740179, 2023). "In addition, we found seven other genes recurrently affected by HBV integration in tumour tissue samples: ECE1, EVI5L, KIF13B, MTX1P1, PLXND1, TECR and USP24." (PMID 37400627, 2023). "Moreover, PLXND1 expression is related with tumor-infiltrating lymphocytes and immunoinhibitors, and TGF-β1 displays the greatest correlations with PLXND1 expression in HCC." (PMID 33489909, 2020). "We demonstrated that PLXND1 is in general ubiquitously expressed in tumor but not normal vasculature, as well as in malignant cells in a wide range of human (tumor) tissues." (PMID 19703316, 2009). "We demonstrate that Plexin D1 is in general ubiquitously expressed in tumor but not normal vasculature, as well as in malignant cells in a wide range of human tissues." (PMID 19703316, 2009). "Neoplastic cells expressed Plexin D1 as well as tumor vasculature, while its expression in nonneoplastic tissue was restricted to a small subset of activated macrophages, which suggests that Plexin D1 may play a significant role in tumor angiogenesis." (PMID 22481931, 2012). "PLXND1 is abundantly expressed in both the vasculature and malignant cells in the majority of clinical tumors, whereas in pre-malignant lesions the protein is present at lower levels or, like in non-tumor related tissues, almost completely absent." (PMID 19703316, 2009).
cancer (15 papers, 2011 to 2025). A tumor composed of atypical neoplastic, often pleomorphic cells that invade other tissues. "Interestingly, in accordance with that, analysis of the TCGA-PRAD database showed that PLXND1 overexpression is significantly associated with a poor disease-free survival in PCa, suggesting that EDCs could participate in cancer aggressiveness (and metastasis) through this new signaling pathway." (PMID 35887249, 2022). "In GEPIA, PLXND1 mRNA expression between tumors and their paired normal tissues across 32 TCGA cancer types were compared." (PMID 33489909, 2020). "For stromal score, NRP1 showed the highest positive correlation across all cancer types (r = 0.59), followed by PLXND1 (r = 0.54), NRP2 (r = 0.50), PLXNC1 (r = 0.48) and PLXNA4 (r = 0.28) (p < 0.0001)." (PMID 32640719, 2020). "Significantly differential expression was found in 12 cancer types, and elevated expression of PLXND1 mRNA was found in HCC compared with normal liver tissues." (PMID 33489909, 2020). "Plexin D1 (PLXND1) is a cellular receptor whose functions have been explored in several human cancers; however, the critical roles of PLXND1 in HCC have rarely been probed." (PMID 33489909, 2020). "It seems that PLXND1 holds therapeutic importance as a biomarker in cancer and may also be a therapeutic target." (PMID 33837646, 2021). "In addition, although Sema3E in embryonic somites is known to repel Plexin-D1-expressing endothelial cells during vasculogenesis, both anti-angiogenic and pro-angiogenic effects of Sema3E have been reported in cancer cells." (PMID 21559368, 2011). "Plexin D1 (PLXND1), a newly identified member of the plexin family of molecules, has been reported to be dysregulated in several cancers." (PMID 33489909, 2020). "The analysis of PLXND1 and TGF-β1expression should be further investigated across multiple cancer types." (PMID 33489909, 2020). "Both NRPs, PLXNA1-A3, PLXNB1-B2, and PLXND1 had relatively higher expression and smaller heterogeneity, while genes PLXNA4, PLXNB3 and PLXNC1 had lower expression across all cancer types but with higher heterogeneity." (PMID 32640719, 2020). "Compared with the adjacent normal liver tissues, significantly upregulated PLXND1 expression in HCC was found in 10 out of 12 clinical cohorts, suggesting that the upregulation of PLXND1 is mainly attributed to the transformation of normal hepatocytes to cancer cells." (PMID 33489909, 2020). "For example, PLXND1 was reported to be the receptor for SEMA3C-SEMA3E, but their expression was not significantly correlated across cancer types (p > 0.05) and they were not clustered together." (PMID 32640719, 2020). "The majority of the tested cancer types showed positive correlation between the expression of NRP1, NRP2, PLXNC1 and PLXND1, negative correlation between expression of PLXNB1, and the three scores." (PMID 32640719, 2020).
cardiovascular disease (2 papers, 2021 to 2022). "This understanding could help to elucidate the regulatory role of PLXND1 signalling in the cardiovascular system and may contribute to the identification of biomarkers and targets for cardiovascular disease diagnosis and treatment." (PMID 33837646, 2021).
retinopathy (2 papers, 2022). "Furthermore, loss of Plexin-D1 function exacerbated brain damage and abnormal behavioral performance, accompanied by lower vessel density in the peri-infarct region, similar to previous observations in a retinopathy model." (PMID 33978913, 2022). "In an oxygen-induced retinopathy model, enhanced Plexin-D1 or intravitreal Sema3E injection prevents abnormal vessel projections and leads to normal vascular remodeling." (PMID 33978913, 2022). "In an oxygen-induced retinopathy model, intravitreal injection of Sema3E selectively suppressed extraretinal vascular outgrowth without affecting the desired regeneration of the retinal vasculature, indicating the therapeutic potential of Sema3E–Plexin-D1 signaling in retinopathy." (PMID 35045890, 2022).
genetic disease (1 paper, 2024). "Nine plexin genes have been identified in humans, but despite the apparent importance of plexins in development, only biallelic PLXND1 and PLXNA1 variants have so far been associated with Mendelian genetic disease." (PMID 38458752, 2024).
heart diseases (1 paper, 2021). "However, the extremely important role of PLXND1 in animal heart development suggests that PLXND1 should be extensively studied in human heart diseases." (PMID 33837646, 2021). "Numerous studies have demonstrated the essential role of PLXND1 and the corresponding SEMA ligands in animal heart development, but their role in human heart diseases has rarely been reported." (PMID 33837646, 2021). "Furthermore, information regarding the mechanisms and detection research investigating the effects of PLXND1 on human heart disease is lacking." (PMID 33837646, 2021).
neurological diseases (1 paper, 2019). "The underlying neurological diseases of 11 patients with anti-plexin D1 antibodies included atopic myelitis, neuromyelitis optica spectrum disorders, multiple sclerosis, neurosarcoidosis, and erythromelalgia." (PMID 31920952, 2019).
PLXND1 also shares sentences with these, for which no sentence is quoted: colon cancers (2 papers); rheumatoid arthritis (2); adenocarcinoma (1); atrial fibrillation (1); Becker muscular dystrophy (1); bladder cancer (1); Cantú syndrome (1); cardiomyopathy (1); CHARGE syndrome (1); congenital heart defects (1); diabetes (1); Duchenne muscular dystrophy (1); heart failure (1); hematological malignancies (1); infantile hemangioma (1); intraepithelial neoplasia (1); Lung (1); metastatic tumors (1); microcephaly (1); multiple sclerosis (1); ovarian adenocarcinoma (1); ovarian cancer (1); pancreatic ductal adenocarcinoma (1); pituitary adenoma (1); pituitary tumor (1); renal carcinoma (1); schizophrenia (1); systemic lupus erythematosus (1); vulvar squamous cell carcinoma (1).